CXCL12 (C-X-C motif chemokine ligand 12)
Diseases named in the same sentence as CXCL12 in open-access papers (continued):
Sharing a sentence is not in itself a finding about the gene and the disease.
tumor (continued). "While our study aims to explore the effects of tumor-derived CXCL12 on the tumor immune microenvironment and TLS formation." (PMID 38767772, 2024). "CAFs generate a substantial amount of extracellular matrix, impeding CTL contact with tumor cells, while also secreting the chemokine CXCL12, which inhibits T cell migration toward the tumor." (PMID 39845973, 2024). "On the one hand, CAFs secrete CXCL12 to cover tumor cells to prevent CD8+ T cells from aggregating near the tumor." (PMID 39680287, 2024). "It has been reported that CAFs are able to secrete factors such as CXCL12 that promote cancer cell proliferation, cancer cell migration and tumour metastasis." (PMID 38766687, 2024). "Dual IHC staining show that tumor infiltrating CD8 T cells localize in proximity of CXCL12+ tumor area." (PMID 38182756, 2024). "Pan-iCAFs are linked to inflammation and secrete high levels of proinflammatory cytokines, such as IL-6, IL-8, and CXCL12, which activate inflammatory responses, promote tumor malignancy, and suppress effective antitumor immunity." (PMID 39835122, 2024). "During injuries, CXCL12 secretion by activated stellate cells pushes NK cells into quiescence and induces dormant tumor cell proliferation, contributing to dormant tumor cell reactivation and metastasis development." (PMID 39682261, 2024). "Another important chemokine CXCL12, plays a key role in the communication of tumor cells and another component of TME and eventually affects tumor angiogenesis, proliferation and chemoresistance." (PMID 39493763, 2024). "CXCR4 plays a critical role in the metastatic spread of different types of tumor cells mediating their homing to organs which express the specific ligand, C-X-C motif chemokine ligand 12 (CXCL12)." (PMID 39465008, 2024). "Despite the established roles of both HMGB1 and CXCL12 in tumor progression and metastatic spread to distal sites, the role of the CXCL12/HMGB1 heterocomplex in cancer has never been investigated." (PMID 38803493, 2024). "In low-stromal tumors, CXCL12 was expressed at low levels, and immune cells infiltrated the tumor area." (PMID 38182756, 2024). "Monocytes are recruited to tumor sites via CCR2 signaling, where tumor cell-secreted TGF-β induces CXCR4, stimulating them to migrate toward CXCL12-expressing perivascular cancer-associated fibroblasts (CAFs)." (PMID 39516356, 2024). "Our data demonstrate that the primary tumor cells have a stronger CXCL12/CXCR4 signaling axis than the CTCs." (PMID 39766093, 2024). "We identified CXCR7, an atypical receptor for CXCL12 predominantly present in tumor cells, as a negative regulator of CXCL12 expression by interfering with extracellular signal-regulated kinase activation." (PMID 38898023, 2024). "It has been elucidated that CAFs influence T cell infiltration through the secretion of various chemokines and cytokines, such as CCL5 and CXCL12, orchestrating the dynamics of the tumor immune microenvironment." (PMID 39545420, 2024). "In conclusion, our findings suggest that β-catenin activation results in DC exclusion into ICC tumor microenvironment with LNM by blocking CXCL12 production." (PMID 38926350, 2024). "Upon interaction with its specific receptors, CXCL12, secreted by either stromal cells or tumor cells, has the potential to activate distinct signaling pathways in various environments." (PMID 38920657, 2024). "CXCR4, a protein found on tumor cells, binds to its receptor CXCL12, presents on bone marrow stromal cells, and induces tumor cell migration to bone." (PMID 38474093, 2024). "The CXCL12/CXCR4 axis has been reported to be a key signalling axis for tumour growth and metastasis through the activation of multiple pathways, such as the p38, ERK1/2 and SAPK/JNK pathways." (PMID 38766687, 2024). "NOX-A12 neutralizes CXCL12 in the blood, and it also releases and sequesters CXCL12 bound to glycosaminoglycans on the surface of tumor endothelial cells at the interface between the blood system and tumor cells." (PMID 38806504, 2024).
tumor (continued). "CXCL12 expression is elevated in multiple tumor types and engages receptors CXCR4 and CXCR7 to promote proliferation and survival of cancer cells and are detected in KS tumors." (PMID 39386738, 2024). "Radiotherapy has been shown to be associated with upregulation of genes involved in proliferation and migration of tumor cells (CXCL12, VEGF-A, TGF-β1, and TNFα)." (PMID 38256907, 2024). "Only when the immune checkpoint therapy was coupled with inhibition of FAP+ CAF-secreted CXCL12 the anti-tumor effect was observed." (PMID 38455762, 2024). "The CXCL12/CXCR4 axis plays a pivotal role in tumor progression and metastasis, making it a promising therapeutic target in cancer." (PMID 39070795, 2024). "CXCL12 signaling in tumor microenvironments participates in signaling with an abundance of cell autonomous, and cell non-autonomous, signals working in concert." (PMID 39766093, 2024). "MIF staining was intense in tumor cells, while CXCL12 and CD3 stainings were relatively weak and diffuse in paraffin sections of control samples." (PMID 38386050, 2024). "In BCa, hypoxia-induced CAF secretion of CXCL12 suppresses the anti-tumour activity of T cells, DCs, NK cells and enhances the pro-tumour activity of Tregs, MDSCs and TAMs." (PMID 38352889, 2024). "The accumulation of MRC1+TIE2HiCXCR4Hi TAMs was accompanied by increased CXCL12 expression in vascularized, well-oxygenated areas after chemotherapy, which was important for tumor revascularization and relapse after chemotherapy." (PMID 39516356, 2024). "CXCL12, with its roles in tumor cell dissemination and immune attack evasion, unsurprisingly has also been associated with a poor prognosis." (PMID 38339310, 2024). "In this study, we developed an injectable bait-and-hook hydrogel (BH-gel) that incorporates doxorubicin liposomes and the tumor chemoattractant CXCL12 for localized drug delivery." (PMID 39771496, 2024). "Not only recruited Treg cells, CXCL12 was also self-secreted by CSCs to strongly induce cancer cell migration from the primary tumor, inhibiting possible interactions with cytotoxic T cells." (PMID 39076974, 2024). "CXCL12 is important for endothelial–fibroblast crosstalk, which is necessary for angiogenesis, tumor growth, and intravasation." (PMID 38959243, 2024). "We found that the Mg‐CaCO3 exhibited rapid and stable hydrogen release capability in the weak acid TME, reduced pro‐tumor and immune suppressive factor generation of CAFs including Cxcl1 and Cxcl12, and augmented anti‐tumor immune activities of CD4+ T cells." (PMID 38757665, 2024). "IL-6, CXCL2, and CXCL12 are cytokines/chemokines that are released by CAFs to regulate tumor immunity and angiogenesis." (PMID 39001545, 2024). "As a result, the formation of the CXCL12/HMGB1 heterocomplex would be possible thanks to the release of CXCL12 by other cell types in the tumor microenvironment." (PMID 38803493, 2024). "Cancer cells were coated with CXCL12, while FAP-positive CAFs were the principal source of CXCL12 in the tumor." (PMID 38892190, 2024). "For instance, myoCAFs and CXCL12+ iCAFs were predominantly abundant in four tumor groups, and SOD2+ iCAFs were exclusively found in the UCCC group." (PMID 39112478, 2024). "The E2F1-mediated inhibitory pathway of WNT5A expression and the CXCL12/CXC- chemokine receptor 4 (CXCR4) chemokine receptor signaling pathway facilitate the invasion of circulating tumor cells into the brain." (PMID 39328239, 2024). "Decreased ketogenesis is a signature of CRC tumor cells, and an increase in ketogenesis using a ketogenic diet (KD) decreases CXCL12 production in tumors." (PMID 38892190, 2024). "Collectively, these findings indicate that the establishment of the self-sustaining TGFB1 and CXCL12 autocrine signaling gives rise to tumor-promoting CAFs (myCAFs)." (PMID 39335478, 2024).
tumor (continued). "These recruited regulatory B cells also induce CXCR4 expression on tumor cell to promote cancer cell metastasis to the lymph node by increase the responsiveness to the pro-metastatic chemokine CXCL12." (PMID 38726320, 2024). "CXCL12 from tumor-associated fibroblasts was found to be able to recruit M2-type macrophages and block CXCR4, the receptor for CXCL12, significantly reducing M2-type macrophage chemotaxis." (PMID 39403370, 2024). "Tumor-related lymphatic vessels control CD8+ T cell migration through CXCL12, and accumulating antigen-specific CD8+ T cells in tumors was crucial for effective immunotherapy." (PMID 39654896, 2024). "The UMAP and heatmap indicated that CXCL12 was predominantly expressed in specific tumor clusters, including Tumor 3 and Tumor 6, as well as in myeloid-cell clusters, while PD-L1 was predominantly expressed in myeloid-cell cluster." (PMID 38898023, 2024). "Although it has long been established that cancer-associated fibroblasts (CAFs), the primary producers of CXCL12 in the TME, can induce EMT in tumor cells, the direct involvement of CXCL12 in EMT has remained unclear." (PMID 39070795, 2024). "Directional migration and invasiveness of tumor cells is enhanced by the CXCL12/HMGB1 heterocomplex, and is CXCR4 dependent." (PMID 38803493, 2024). "CXCR4 selectively binds the CXC chemokine stromal cell-derived factor-1 (SDF-1), also known as CXCL12, and plays a crucial role in several biological processes, including in cancer biology, where it was associated with tumour dissemination and metastasis." (PMID 38534365, 2024). "By secreting CXCL12/SDF1, CAFs recruit monocytes to the tumor site, which are then induced to differentiate into MDSCs through IL-6-mediated STAT3 activation, thus altering CAR-T cell proliferation and function and diminishing their therapeutic effect." (PMID 39136031, 2024). "All TAM subsets have varying levels of the chemokine CXCL12, which is involved in tumor proliferation, immune inhibition by exclusion of NK cells and T cells from tumor areas, and homing of cancer cells to metastasis-prone tissues." (PMID 39256888, 2024). "Several studies have demonstrated that CXCL12 is overexpressed in tumor tissues of various human malignancies." (PMID 39070795, 2024). "Secretion of the chemokine SDF-1 through the activation of CXCR4/CXCL12 signaling also has a positive correlation with increased Treg number in the tumor microenvironment." (PMID 38571964, 2024). "Highly involved in tumor progression and metastasis from previous research, CXCL12/CXCR4 axis is regarded as one promising therapeutic target in cancer." (PMID 38833154, 2024). "CXCR4 also contributes to immune suppression, supports tumor growth, and has the potential to chemoattract cancer cells to organs that produce its ligand, CXCL12, where cancer cells can establish secondary tumors." (PMID 38831458, 2024). "Further, CAFs increase ECM secretion, creating a physical barrier to prevent immune cell infiltration and migration within the tumor, based on the secretion of chemokine CXCL12, which is known to promote angiogenesis and tumor growth." (PMID 39186169, 2024). "As discussed, the CXCL12/CXCR4 axis is involved in tumor angiogenesis and metastasis of tumor cells to distant organs." (PMID 39070795, 2024). "Adding back CXCL12 to these tumor spheroid models restored T-cell functionality and reversed the resistant phenotype." (PMID 38339310, 2024). "Fibroblast production of CXCL12/SDF-1 was shown to promote tumor cell proliferation by the activation of the CXCR4/ErbB2 axis." (PMID 38360674, 2024). "FAP-positive CAFs inhibit T cell infiltration into the tumor through CXCL12, and depletion of these fibroblasts or targeting of CXCL12 increases the sensitivity to immune checkpoint blockade of PC in preclinical models." (PMID 38352864, 2024).
tumor (continued). "In the pre-metastatic niche, CXCL12 recruits circulating tumor cells with high CXCR4 and low Prrx1 expression from the bloodstream, ultimately promoting the metastatic colonization of distant organs." (PMID 38920657, 2024). "CXCL12-rich CAFs can impede CXCR4-expressing T cells from accessing tumor cells, hindering T cell infiltration." (PMID 39545420, 2024). "Through complex interactions with molecules such as DARPP-32, STAT-3, CXCR4, and CXCL-12, dopamine contributes to cancer cell invasion, immune response modulation, and tumor growth by stabilizing key proteins involved in angiogenesis and metastasis." (PMID 39767693, 2024). "Mechanistically, miR-101 suppresses T-ALL tumor development by targeting the CXCL12/ACKR3/STAT3 signaling pathway." (PMID 38920657, 2024). "CAFs have been reported as a key component of the TME and are a strong source of chemokine CXCL12 and rich in alpha smooth muscle actin-positive cells, which promote tumor growth and angiogenesis and remodel the ECM." (PMID 38671924, 2024). "Further analysis of ccRCC suggested that these mature plasma cells within the TLS are guided by CXCL12+ fibroblasts to migrate deeper into tumor foci while producing IgG and IgA antibodies and boosting anti-tumor effects." (PMID 39107856, 2024). "Chemokines, such as CCL2, CCL5, and CXCL12, are vital for the recruitment of monocytes into tumor tissues." (PMID 39516356, 2024). "Here, we have demonstrated that the expression of Notch3 was positively associated with the level of soluble tumor-derived chemotactic factors, such as CSF1, CXCL12 and CCL2, which are chemotactic stimulus for macrophage recruitment." (PMID 36647017, 2023). "NFκB in PSCs increases CXCL12 expression thereby reducing cytotoxic T cell infiltration in the tumor and decreasing the killing effect on cancer cells, thus promoting tumor growth." (PMID 37409257, 2023). "Because C-X-C motif chemokine 12 (CXCL12) secretion by PSCs and CAFs is associated with tumour progression, the study aimed to measure this as an indication of the interruption of this pathway by the treatments." (PMID 37627163, 2023). "RT-activated CAFs were found to excrete increased levels of CXCL12/SDF-1, ultimately promoting a mesenchymal phenotype in cancer cells and aiding to the overall tumor progression." (PMID 37170098, 2023). "Autocrine CXCL12 signaling in breast fibroblasts initiated and maintained the pro-tumor CAF phenotype." (PMID 37784082, 2023). "In subdermal tumor xenograft mice, CXCL12 overexpression induced an immunosuppressive microenvironment and reduced CTL infiltration by recruiting immunosuppressive cells." (PMID 37497001, 2023). "When combined with PD-1 blockers, the CXCL-12 inhibitor induced higher T-cell activation within the spheroid and decreased tumor volume than single-agent treatments." (PMID 38106674, 2023). "Exposure to TGF-β in the tumour increases macrophage sensitivity to C-X-C chemokine ligand type 12 (CXCL12) and drives them towards a pro-tumour phenotype." (PMID 36972297, 2023). "In vivo experiments demonstrated that blocking CXCL12 inhibited tumor growth, reduced tumor PDL1 expression and increased immune cell infiltration." (PMID 38001512, 2023). "On the other hand, we identified repressed genes such as Mdk, Fap, Mmp9, Itga6, and Cxcl12, known as mediators of tumor growth, migration, invasion, and fibrosis." (PMID 36765032, 2023). "In a model of liver metastasis, it was shown that the CXCR4 chemokine receptor on tumor cells and its ligand CXCL12 expressed by endothelial cells significantly promote tumor cell transendothelial migration." (PMID 37240247, 2023). "In cancer, CXCL12 acts as a communication bridge between tumor cells and their environment, conferring resistance to ICI through T-cell exclusion in preclinical models." (PMID 37372349, 2023). "Recent studies suggest that CXCL12 derived from tumor stromal cells contributes to tumor progression, but our results are contradictory to those observations." (PMID 36300800, 2023).
tumor (continued). "Functional co-culture experiments show that CD26+ NFs transition into pro-tumorigenic iCAFs which recruit myeloid cells in a CXCL12-dependent manner and enhance tumor cell invasion via matrix-metalloproteinase (MMP) activity." (PMID 36635273, 2023). "RHBDD2-CKO-induced upregulation of CXCL12 in stromal cells leads to anticancer drug resistance via activating the PI3K-Akt-mTOR pathway in tumor cells." (PMID 37264057, 2023). "Downregulation of CXCL12 in OS facilitates the release of tumor cells from the bone and metastasis to other tissues." (PMID 37575253, 2023). "EC-derived PDGF-B signaling functions as another key regulator of tumor cell dormancy and therapy resistance by acting on pericytes that secrete quiescence-inducing factors, such as CXCL12." (PMID 37446097, 2023). "CXCL12 is the main driver of vascular permeability, which promotes the infiltration of tumor cells and enables tumor cells to escape from the primary site to other distant organs." (PMID 37978384, 2023). "For instance, the log-ncpm for CXCL12 gRNA #B11840 in one 6-TG-treated tumour was 26.5, while zero counts were detected in another 6-TG-treated tumour." (PMID 37684549, 2023). "CXCL12 up‐regulate the anti‐apoptotic proteins Bcl‐2 and Survivin in tumor cells, resulting in drug resistance." (PMID 37578396, 2023). "A nanosystem delivering FAP antibodies can inactivate CAF by downregulating the expression of CXCL12 to modulate the tumor microenvironment of PCa." (PMID 37784082, 2023). "The CXCL12/CXCR4 axis plays a crucial role in tumor–stromal cell interactions, leading to progression-related behaviors such as angiogenesis, migration, and metastasis." (PMID 37444525, 2023). "In cancer cells, the HIF-1α is overexpressed, which regulates tumor survival-related genes, such as CXCL12 and CXCR4." (PMID 36207479, 2023). "In recent years, there has been a significant advancement in the understanding of the role of CXCL12 and its receptor in tumor progression." (PMID 37497001, 2023). "They observed immune control only after depleting FAP+CAFs, which were responsible for overexpression of CXCL12 that restricted recruitment of T cells into the tumor site." (PMID 38313431, 2023). "For example, CAFs in the tumor stroma secrete stromal cell-derived factor (SDF-1)/CXCL12 and recruit CXCR4+ EPCs, thereby promoting new vessel formation." (PMID 37350937, 2023). "Signaling by the chemokine receptor CXCR4 after binding the chemokine CXCL12 (SCF-1) triggers increased tumor proliferation, survival, and chemotaxis." (PMID 37114134, 2023). "Lower levels of CXCL12 expression were positively correlated with poor differentiation, mode of invasion, and tumor recurrence." (PMID 36300800, 2023). "Seventy patients (85.3%) showed positive expression of CXCL12 in tumor cells, and fifty-four patients (65.9%) showed positive expression of CXCL12 in cancer-associated fibroblasts." (PMID 37227446, 2023). "CD26+ NFs enhanced the invasive properties of tumor cells via matrix metalloproteinase (MMP) activity and co-cultures of CD26+ NFs and tumor cells recruited CD11b+ myeloid cells in a CXCL12-dependent manner." (PMID 36635273, 2023). "CXCL12, known as stem cell-derived factor 1, has angiogenesis property and regulate tumor progression." (PMID 37393391, 2023). "It was proven by upregulated activation of the regulon or mRNA expression of JUN of CXCL12+ iCAF in the tumor tissues of patients with advanced-stage CRC." (PMID 37360193, 2023). "In a paracrine manner, CXCL12 attracts CXCR4-expressing tumour cells to a new tumour niche, resulting in tumour cell invasion and metastasis." (PMID 37509322, 2023). "In another study, M-E5 has a higher affinity for CXCR4 overexpressing human solid tumor cells and a stronger ability to inhibit CXCL12-induced tumor cell migration compared with E5." (PMID 36762192, 2023).